KIF21A (kinesin family member 21A)
Description:
Processive microtubule plus-end directed motor protein involved in neuronal axon guidance. Is recruited by KANK1 to cortical microtubule stabilizing complexes (CMSCs) at focal adhesions (FAs) rims where it promotes microtubule capture and stability. Controls microtubule polymerization rate at axonal growth cones and suppresses microtubule growth without inducing microtubule disassembly once it reaches the cell cortex.
Synonyms: FLJ20052; CFEOM1; FEOM1; FEOM3A
Tractability: PROTAC: ubiquitination databases record sites on it; its protein half-life has been measured.
Target class: Other cytosolic protein
Gene: Protein-coding gene on chromosome 12 (39,293,228 to 39,443,718, reverse strand). Ensembl gene ENSG00000139116.
Subcellular location: Cytoplasm, cytoskeleton; Cytoplasm, cell cortex; Cell projection, axon; Cell projection, dendrite; Cell projection, growth cone
Subcellular location (Human Protein Atlas): Cytosol
Pathways (Reactome):
Hemostasis: Kinesins
Vesicle-mediated transport: COPI-dependent Golgi-to-ER retrograde traffic
Gene Ontology:
Molecular function: ankyrin repeat binding; plus-end-directed microtubule motor activity; protein binding; ATP binding; microtubule binding; microtubule motor activity
Biological process: cortical microtubule organization; regulation of axon guidance; regulation of microtubule depolymerization; regulation of microtubule polymerization; establishment or maintenance of cell polarity; anterograde axonal transport; microtubule-based movement
Cellular component: axonal growth cone; cell cortex; kinesin complex; microtubule associated complex; axon; axon cytoplasm; cytoskeleton; dendrite; growth cone; presynapse
Genetic constraint (gnomAD): Loss-of-function variants: 73 observed, 146.04 expected, observed/expected ratio (o/e) 0.5, 90% interval 0.41 to 0.61. The upper end of that interval is the gene's LOEUF score, 0.61, which puts it in group 2 of 6, group 1 being the genes least tolerant of losing a copy. Missense variants: 1,291 observed, 1,637 expected, observed/expected ratio (o/e) 0.79, 90% interval 0.75 to 0.83. Synonymous variants: 539 observed, 555.8 expected, observed/expected ratio (o/e) 0.97, 90% interval 0.9 to 1.04.
Gene-disease validity (ClinGen):
ClinGen rates the evidence that KIF21A causes each of these diseases.
congenital fibrosis of extraocular muscles (autosomal dominant): Definitive.
Homologues: Orthologues: chimpanzee KIF21A (99% identical), macaque KIF21A (99% identical), dog KIF21A (97% identical), pig KIF21A (96% identical), rabbit KIF21A (94% identical), mouse Kif21a (94% identical), rat Kif21a (92% identical), guinea pig KIF21A (91% identical), tropical clawed frog kif21a (79% identical), zebrafish kif21a (68% identical), zebrafish si:cabz01066312.1 (17% identical). Paralogues in human: KIF21B (59% identical), KIF4A (24% identical), KIF4B (24% identical), CENPE (20% identical), KIF27 (20% identical), KIF7 (19% identical), KIF15 (16% identical), KIF13B (16% identical), KIF1A (16% identical), KIF1B (16% identical), KIF13A (15% identical), KIF5A (15% identical), and 29 more.
Diseases named in the same sentence as KIF21A in open-access papers:
KIF21A is named in the same sentence as 42 diseases in open-access papers, as found by Europe PMC text mining. Sharing a sentence is not in itself a finding about the gene and the disease. The quoted sentences say what the papers report.
congenital fibrosis of the extraocular muscles type 1 (9 papers, 2010 to 2024). "Gain-of-function variants in KIF21A are associated with congenital fibrosis of the extraocular muscles type 1 (CFEOM1) which is an autosomal dominant neurodevelopmental disorder affecting the oculomotor nerve." (PMID 37932480, 2023). "Congenital fibrosis of the extraocular muscles type 1 (CFEOM1) is known to be caused by mutations in KIF21A or TUBB3 or other known genes (SALL4, CHN1, HOXA1)." (PMID 29110737, 2017). "Point mutations in the KIF21A gene cause congenital fibrosis of the extraocular muscles type 1 (CFEOM1) by disrupting the autoinhibitory interaction between the motor domain and a regulatory region in the stalk." (PMID 27485312, 2016). "Congenital fibrosis of the extraocular muscles (CFEOM) affects cranial nerves 3 and 4 and is caused by autosomal dominant missense variants in KIF21A, TUBB3, TUBB2B or TUBA1A or autosomal recessive variants in PHOX2A." (PMID 38500555, 2023). "Characterized by congenital, non-progressive, restrictive ophthalmoplegia and ptosis, congenital extraocular muscle fibrosis is an autosomal dominant disorder caused by mutations of the KIF21A gene." (PMID 38975553, 2024). "Enhanced KIF21B expression has been associated with severe AD pathology, while KIF21A is linked to congenital fibrosis of the extraocular muscles type 1 (CFEOM1), a disease characterized by absence of motor neurons of the midbrain." (PMID 37016304, 2023). "Kif21a is linked to congenital fibrosis of the extraocular muscles type 1 (CFEOM1), a disease characterised by absence of motor neurons of the midbrain and in the superior division of the oculomotor nerve." (PMID 25274010, 2014).
ptosis (3 papers, 2013 to 2023). The drooping of the upper eyelid. "As seen from the established Kif21a R954W knock-in mice model, the mice presented the same phenotypes (ptosis and restricted upgaze reflect) as CFEOM1 patients." (PMID 36138147, 2023). "Although PAX6 mutations may cause the phenotype of congenital ptosis, comparing the feature of ptosis with his mother, we didn’t find his bilateral ptosis was more serious than his mother’s, which suggested that his bilateral ptosis with ophthalmoplegia was caused by the KIF21A mutation." (PMID 23799907, 2013).
lung carcinoma (2 papers, 2015 to 2025). "KIF21A, one of these mutated genes, has been shown to be down regulated in a murine lung cancer model due to the aberrant methylation of its promoter." (PMID 26620706, 2015). "Previous investigations have shed light on the role of KIF21A in lung cancer." (PMID 40098701, 2025). "The expression of KIF21A decreases owing to DNA methylation in patients with lung cancer." (PMID 40098701, 2025).
schizophrenia (2 papers, 2021 to 2024). A major psychotic disorder characterized by abnormalities in the perception or expression of reality. "In humans, Plscr3 and Sar1b are linked to obesity and lipid metabolic disease, respectively, Kif21a is linked to ocular disease, and Nlgn2 is linked to schizophrenia (MGI)." (PMID 38968323, 2024).
Strabismus (2 papers, 2021 to 2025). A misalignment of the eyes so that the visual axes deviate from bifoveal fixation. "Recently, a case of a KIF21A-associated syndromic phenotype characterized by progressive peripheral neuropathy, hypoplasia of the splenium of the corpus callosum, and strabismus has been described described." (PMID 41282472, 2025).
Akinesia (1 paper, 2023). Inability to initiate changes in activity or movement and to perform ordinary volitional movements rapidly and easily. "While human KIF21A-fetal akinesia variants are predicted to result in complete loss of KIF21A protein, how absence of KIF21A results in early postnatal death and how it may alter peripheral and central nervous system development in mice and humans remains to be elucidated." (PMID 37600020, 2023).
aniridia (1 paper, 2013). Aniridia is a congenital ocular malformation characterized by the complete or partial absence of the iris. "He inherited the c.2860C > T (p.Arg954Trp) mutation in KIF21A from his mother, who also had CFEOM1, and the c.745delC (p.Leu249TyrfsX22) mutation in PAX6 from his father who had congenital aniridia." (PMID 23799907, 2013). "In summary, we identified a 7 year old male with aniridia and congenital fibrosis of the extraocular muscles as a result of independent mutations in the PAX6 and KIF21A genes, inherited independently from his father and mother." (PMID 23799907, 2013).
Charcot-Marie-Tooth disease type 2A (1 paper, 2022). "Charcot-Marie-Tooth disease type 2A can be caused by mutations in Kif1b, congenital fibrosis of the extraocular muscles can be caused by mutations in Kif21a, and a loss-of-function mutation in Kif5a motor domain can result in hereditary spastic paraplegia." (PMID 35259089, 2022).
congenital fibrosis of extraocular muscles 1 (1 paper, 2012). "In human, mutations in the KIF21A gene were identified as responsible for congenital fibrosis of extraocular muscles 1 (CFEOM1)." (PMID 22933835, 2012).
distal arthrogryposis (1 paper, 2025). A muscle tissue disease characterized by congenital joint contractures of hand and feet. "The phenotypic spectrum of the KIF21A-related disorders is broad and includes CFEOM, and several reports linking them to inherited distal arthrogryposis." (PMID 41282472, 2025).
distal motor neuropathy (1 paper, 2025). "We report the second case of early-onset distal motor neuropathy associated with the KIF21A gene." (PMID 41282472, 2025). "This study adds evidence that the KIF21A gene phenotypic spectrum includes distal motor neuropathy and suggests that it should be considered for genetic testing of peripheral neuropathies." (PMID 41282472, 2025). "Our case supports expansion of the KIF21A-related phenotype to include distal motor neuropathy without brain malformations, in addition to multiple reports of other KIF21-associated syndromic phenotypes." (PMID 41282472, 2025).
glaucoma (1 paper, 2022). Increased pressure in the eyeball due to obstruction of the outflow of aqueous humor. "Several of these ExWAS significant IOP genes, such as PTPRB, KIF21A, DNTT, also show a significant association with glaucoma in UKB with P = 3.26 × 10−5, 0.009, 0.007, respectively." (PMID 36450729, 2022).
Intellectual disability (1 paper, 2023). "The recently reported KIF21A L685P substitution results in a syndromic CFEOM human phenotype that is very similar to the syndromic TUBB3-CFEOM phenotypes, with facial weakness, progressive axonal polyneuropathy, and intellectual disability in addition to CFEOM." (PMID 37600020, 2023).
nephrotic syndrome (1 paper, 2023). A collection of symptoms that include severe edema, proteinuria, and hypoalbuminemia; it is indicative of renal dysfunction. "Taken together, our data identified Kif21a as a novel nephrotic syndrome associated candidate playing a major role in proper GFB function in zebrafish." (PMID 37932480, 2023). "Given the results presented in our study and those published in the literature, individuals with nephrotic syndrome may have pathogenic variants in KIF21A, encoding a direct interaction partner of KANK1 and KANK2." (PMID 37932480, 2023). "It is tempting to speculate that mono- and/or biallelic pathogenic variants in KIF21A may cause proteinuria or nephrotic syndrome in affected individuals." (PMID 37932480, 2023).
Nystagmus (1 paper, 2024). Rhythmic, involuntary oscillations of one or both eyes related to abnormality in fixation, conjugate gaze, or vestibular mechanisms. "In a previous report, nystagmus was present in patients with TUBB3 mutations; however, in our patients, nystagmus was present not only in patients with TUBB3 mutations, but also in patients with KIF21A mutations." (PMID 39148141, 2024).
optic nerve hypoplasia (1 paper, 2021). "However, using MRI studies, optic nerve hypoplasia has previously been described in patients with KIF21A mutations and TUBB3 mutations." (PMID 33806565, 2021). "Clinical examination aided by fundus photos have also been used to describe disc excavation and optic nerve hypoplasia in CFEOM1 and CFEOM3; however, sequence analysis only identified one patient with a KIF21A mutation." (PMID 33806565, 2021).
pancreatic ductal adenocarcinoma (1 paper, 2022). An infiltrating adenocarcinoma that arises from the epithelial cells of the pancreas. "For example, the expression level of KIF21A was significantly related to the clinical prognosis outcome of pancreatic ductal adenocarcinoma (PDAC) patients; patients with increased levels of KIF21A had shorter overall survival (OS) time." (PMID 35720415, 2022).
situs inversus (1 paper, 2021). A congenital condition in which there is complete right-to-left reversal of the position of the major thoracic and abdominal organs (that is, they are arranged in a mirror image of the normal positioning). "Whether this process is perturbed due to KIF21A mutations resulting in situs inversus of retinal vessels requires further study." (PMID 33806565, 2021).
ZIKV infection (1 paper, 2020). "KIF21A is a member of the KIF4 subfamily of kinesin-like motor proteins that has been shown to affect axon and growth cone morphology, presenting the possibility that the alternative splicing of KIF21A as a result of ZIKV infection influences neurodevelopment." (PMID 32380717, 2020).
tumor (4 papers, 2019 to 2025). "Notably, there was a significant positive association between KIF21A and PIGH with activated NK cells, which are immune cells with broad-spectrum anti-tumor effects, while RPS6KA2 was negatively correlated with its activation." (PMID 40098701, 2025). "Also, the set of variants of the tumor sample that were lost in CDS17 and T-CDS17 cells (Clusters 10–14) included a mutation in Kinesin Family Member 21A (KIF21A) previously reported in COSMIC for other types of tumor and other 13 unreported mutations." (PMID 30987403, 2019).
cancer (2 papers, 2012 to 2025). A tumor composed of atypical neoplastic, often pleomorphic cells that invade other tissues. "In addition to the cancer connections studied here, our results provide clues to the etiology of rare genetic disorders caused by mutations in KIF21A and TPM2." (PMID 23071517, 2012). "Among these biomarkers, KIF21A plays a pivotal role in microtubule assembly, and research has shown that its activity is significantly decreased in several cancers, subsequently influencing the regulation of cell polarity and migration." (PMID 40098701, 2025). "Otherwise, practically nothing is known about KIF21A and our results strongly encourage further examination of its role in normal and cancer cells." (PMID 23071517, 2012). "Thus, all siRNAs sensitized cancer cells to one or several lysosome-disrupting drugs with the strongest effects observed in cells lacking KIF11 or KIF21A." (PMID 23071517, 2012).
infection (2 papers, 2020 to 2021). The state of being infected such as from the introduction of a foreign agent such as serum, vaccine, antigenic substance or organism. "We also showed that ZIKVPR infection led to the increased exclusion of exon 27 in KIF21A." (PMID 32380717, 2020). "SARS-CoV-2 might also be using axonal transport proteins for its spread and infection in the neuron, as demonstrated by the mimicry of tubulin, KIF1A, KIF21A, and dynein." (PMID 33833673, 2021).
neurodevelopmental disorder (2 papers, 2019 to 2021). A behavioral and cognitive disorder with onset during the developmental period that involves impaired or aberrant development of intellectual, motor, or social functions. "They play important roles in neurons, as suggested by inhibition of axon growth and regeneration through the ARF activator Efa6 in C. elegans, and by neurodevelopmental disorders linked to the mammalian kinesin Kif21A." (PMID 31718774, 2019).
neurologic diseases (2 papers, 2020 to 2021). "HNRNPDL and RBM39 function in transcriptional regulation, HNRNPDL and SRSF2 regulate alternative splicing, MPRIP is involved in stress granule formation, CHID1 has a role in pathogen sensing, and KIF21A has been implicated in neurological diseases." (PMID 32380717, 2020). "Patient 1’s CSF also enriched TCF4 and KIF21A peptides relative to CSF samples from pediatric patients with other neurologic diseases." (PMID 34694339, 2021).
kidney disease (1 paper, 2023). "In this study, we demonstrate a novel role of Kif21a in the establishment of a functional glomerular filtration barrier (GFB) in zebrafish, a suitable vertebrate in vivo model that is well-accepted for the analysis of human kidney disease such as proteinuric disorders." (PMID 37932480, 2023).
neurodegenerative disease (1 paper, 2022). A disorder of the central nervous system characterized by gradual and progressive loss of neural tissue and neurologic function. "This expression profile fits aptly to the correlation of increased Kif21a expression to axonal guidance abnormalities and neurodegenerative diseases." (PMID 36359890, 2022).
KIF21A also shares sentences with these, for which no sentence is quoted: Fibrosis of (2 papers); ophthalmoplegia (2); aneurysm (1); Autoimmunity (1); autosomal dominant lower extremity-predominant spinal muscular atrophy-2A (1); Bardet-Biedl syndrome (1); COVID-19 (1); Down syndrome (1); Duane retraction syndrome (1); genetic disorders (1); hereditary spastic paraplegia (1); liver cirrhosis (1); Obesity (1); peripheral neuropathy (1); Pitt-Hopkins syndrome (1); psychiatric disorder (1).